IL13RA2 (interleukin 13 receptor subunit alpha 2)
Description:
Cell surface receptor that plays a role in the regulation of IL-13-mediated responses. Functions as a decoy receptor that inhibits IL-13- and IL-4-mediated signal transduction via the JAK-STAT pathway and thereby modulates immune responses and inflammation. Serves as a functional signaling receptor for IL-13 in an alternative pathway involving AP-1 ultimately leading to the production of TGFB1.
Synonyms: CD213a2; IL-13R; IL13BP; CT19
Tractability: Antibody: UniProt places it where antibodies can reach, with high confidence; its Gene Ontology location is reachable by antibodies, with high confidence; UniProt predicts a signal peptide or a membrane-spanning region; the Human Protein Atlas places it where antibodies can reach. Other modalities: a drug acting on it is in phase 2 or 3 trials.
Target class: Membrane receptor
Gene: Protein-coding gene on chromosome X (115,003,975 to 115,019,977, reverse strand). Ensembl gene ENSG00000123496.
Subcellular location: Cell membrane
Subcellular location (Human Protein Atlas): Cell Junctions; Plasma membrane; Nucleoplasm; Vesicles
Pathways (Reactome):
Immune System: Interleukin-4 and Interleukin-13 signaling
Gene Ontology:
Molecular function: cytokine receptor activity; protein binding; cytokine binding
Biological process: interleukin-13-mediated signaling pathway; apoptotic process; cytokine-mediated signaling pathway; ERK1 and ERK2 cascade; negative regulation of inflammatory response; positive regulation of cell population proliferation; positive regulation of ERK1 and ERK2 cascade; regulation of transforming growth factor beta1 production; transforming growth factor beta1 production
Cellular component: plasma membrane; receptor complex; external side of plasma membrane; extracellular region; membrane
Homologues: Orthologues: chimpanzee IL13RA2 (98% identical), macaque IL13RA2 (91% identical), pig IL13RA2 (76% identical), guinea pig IL13RA2 (64% identical), rabbit IL13RA2 (62% identical), mouse Il13ra2 (58% identical), rat Il13ra2 (56% identical), tropical clawed frog il13ra2 (34% identical), zebrafish il13ra2 (32% identical). Paralogues in human: IL6ST (16% identical), IL12RB2 (15% identical), PRLR (15% identical), LIFR (15% identical), IL13RA1 (14% identical), OSMR (14% identical), CRLF1 (14% identical), CSF2RA (13% identical), IL23R (13% identical), LEPR (13% identical), GHR (13% identical), CSF3R (12% identical), and 11 more.
Diseases named in the same sentence as IL13RA2 in open-access papers:
IL13RA2 is named in the same sentence as 135 diseases in open-access papers, as found by Europe PMC text mining. Sharing a sentence is not in itself a finding about the gene and the disease. The quoted sentences say what the papers report.
glioblastoma (222 papers, 2010 to 2025). The most malignant astrocytic tumor (WHO grade IV). "IL-13Rα2 is a high affinity membrane receptor that is overexpressed in glioblastoma, and is associated with poor outcome, mesenchymal gene profile, immunity, and the tumor microenvironment, which make it an important therapeutic target." (PMID 41208963, 2025). "Key targets for CAR T-cell therapy include EGFRvIII, a common mutation in glioblastoma, and IL13Rα2, an overexpressed receptor in glioblastoma that has been implicated in its aggressive behavior." (PMID 39796773, 2025). "We isolated five scFvs, with varying affinity for the glioblastoma-associated antigen IL13Rα2, that recognized different epitopes of the receptor and developed CAR-T cells from the scFvs." (PMID 37563127, 2023). "Like EGFRvIII, IL-13Rα2 overexpression in glioma is associated with poor patient prognosis; however, its role in glioblastoma has remained controversial." (PMID 37046685, 2023). "BiCAR-T cells simultaneously expressing HER2 and IL13Rα2 CAR molecules showed higher efficiency in removing glioblastoma tumor cells and lower antigen escape variants than CAR-T cells targeting HER2 alone or pooled CAR-T cells in mouse xenograft models." (PMID 35326556, 2022). "Glioblastoma mesenchymal subtype is characterized by proinflammatory nature and is associated with overexpression of IL13Rα2." (PMID 35612318, 2022). "Glioblastoma, one of the most aggressive primary brain tumors, has shown antigen loss in mice after treatment with anti-IL13Rα2-CAR.IL15 T cells due to downregulated IL13Rα2 expression." (PMID 34831068, 2021). "Alternatively, CAR T cell therapies can target IL13Rα2, which is overexpressed in 58% of glioblastomas and is associated with poor prognosis and a mesenchymal gene signature." (PMID 34054867, 2021). "Recent articles, for example, highlight the role of receptors such as interleukin 13 receptor alpha 2 (IL-13RA2) as a tumor-associated receptor over-expressed in most patients with glioblastoma as well as the overexpression of EphA2 and EphA3 receptors." (PMID 33352931, 2020). "Newman and colleagues reported a co-activation of proliferation caused by interaction IL13Rα2 and EGFRvIII, a glioblastoma exclusive variant of the EGF receptor." (PMID 31561550, 2019). "Interleukin-13 receptor alpha 2 (IL13Rα2) is a cancer associated receptor expressed in glioblastoma and other invasive cancers." (PMID 29304038, 2018). "A complete response to CAR T cell therapy of recurrent multifocal glioblastoma was achieved using autologous T cells genetically-redirected to the tumor-associated antigen interleukin-13 receptor alpha 2 (IL13Rα2)." (PMID 30559740, 2018). "The CTLs are subsequently activated to destroy tumor cells containing glioblastoma-associated antigens such as IL-13Rα2 or EGFRvIII." (PMID 30248992, 2018). "Moreover, elevated IL-13Rα2 expression correlated with decreased survival rates in glioblastoma and renal cell carcinoma patients and a high risk of brain metastasis from breast cancer." (PMID 39598436, 2024). "Plasma IL13RA2 levels are linked to overall survival of patients with glioblastoma." (PMID 39220137, 2024). "Furthermore, elevated IL-13Rα2 mRNA expression was significantly associated with reduced survival in glioblastoma and adrenocortical carcinoma." (PMID 39598436, 2024). "It has been confirmed from both in vitro and in vivo studies that hybridoma cell line development secretes antibodies that are specific and exhibit high affinity for antigen IL13Rα2-associated with tumors and thus provides a novel therapeutic strategy for glioblastoma." (PMID 35612318, 2022). "Glioblastoma-associated antigens, including IL-13 receptor subunit-α2 (IL-13Rα2) and EGFR variant III (EGFRvIII), are also presented on tumor cell surfaces independent of major histocompatibility complex (MHC) class I, a necessary requirement for T cell recognition." (PMID 30248992, 2018).
glioblastoma (continued). "Interleukin 13 receptor alpha 2 (IL13Rα2) is a relevant therapeutic target in glioblastoma (GBM) and other tumors associated with tumor growth and invasion." (PMID 37963919, 2023). "Several chimeric antigen receptor (CAR)-T cell therapy clinical trials have been launched to target glioblastoma-associated surface antigens, e.g., IL13Rα2, HER2 and GD2, with fewer focusing on the glioblastoma-specific but subclonal antigen, EGFRvIII10,11." (PMID 39893177, 2025). "IL13RA2 is a target of cell-based immunotherapies, and a phase I clinical trial of IL13RA2 directed CAR-T cells for recurrent high-grade glioblastoma was recently completed (NCT02208362)." (PMID 41408661, 2025). "The use of CAR-T cells in glioblastoma is based on targeting the tumor-specific or tumor-enriched antigens like IL-13Rα2, EGFR/EGFRvIII, HER2, CD70, B7-H3, and CD133/CD44." (PMID 41208963, 2025). "A phase I clinical trial evaluated intrathecal administration of dual-target CAR-T cells directed against two glioblastoma-associated antigens: epidermal growth factor receptor (EGFR) and interleukin 13 receptor α2 (IL13Rα2)." (PMID 41301694, 2025). "The study demonstrated preliminary safety and bioactivity of CART EGFR IL13Rα2 cells in recurrent glioblastoma, but evidence of efficacy remains inconclusive and requires confirmation in larger cohorts with longer follow-up periods." (PMID 41301694, 2025). "The choice of dual targeting (EGFR + IL13Rα2) was deliberate: both antigens are frequently co-expressed in glioblastoma, reducing the likelihood of antigen escape—a common failure mode in single-target CAR-T therapies." (PMID 41154636, 2025). "In the realm of solid tumors, laboratory investigations have explored various tandem CAR combinations, such as HER2/IL13Ra2 for glioblastoma treatment and HER2/MUC1 for breast cancer therapy." (PMID 40382583, 2025). "Two reports, in glioblastoma and lung epithelial cells, showed interactions between the cytoplasmic domains of IL13RA2 and IL4R that interfere with IL4-driven STAT6 signaling." (PMID 40663259, 2025). "Conversely, a large number of glioblastoma tumor cells express ephrin type A receptor 2 (EphA2) and interleukin 13 receptor α2 (IL13Rα2)." (PMID 40308611, 2025). "In a clinical trial (NCT02208362), a patient with recurrent multifocal glioblastoma received IL13Rα2-targeted CAR T cells via intracranial infusions over 220 days." (PMID 40223940, 2025). "Few studies have characterised IL-13 expression in gliomas with the majority of research focused on the IL-13 receptor subunit alpha-2 (IL-13Rα2), which was shown to be aberrantly expressed in almost 80% of glioblastoma samples." (PMID 41034696, 2025). "Promising results emerged from preclinical studies where HER2- or IL13Ra2-targeted CAR-T cells were directly introduced into brain tissue to treat glioblastoma and breast cancer brain metastases." (PMID 40382583, 2025). "Clinical studies have shown tumor regression in glioblastoma patients treated with IL13Rα2-targeted CAR-T cells." (PMID 40855097, 2025). "For example, pre-clinical models have demonstrated the superior therapeutic efficacy of intraventricular injection of CAR-T cells targeting HER2 and IL13Rα2 in breast cancer brain metastases and glioblastoma, respectively." (PMID 40861448, 2025). "Chimeric antigen receptor (CAR)-T cell therapy targeting IL13Rα2 has demonstrated potential in treating glioblastoma and other IL13Rα2-positive cancers." (PMID 40855097, 2025). "In the glioblastoma study, CARs targeting IL13Ra2 and HER2 decreased antigen escape and boosted anti-tumor activity." (PMID 38892913, 2024). "Interleukin-13 Receptor Alpha 2 (IL-13Rα2) is highly expressed in glioblastoma tumor cells but is seldom found in normal brain cells, making it a compelling target for CAR-T cell therapy in glioblastoma cancer." (PMID 39335671, 2024).
glioblastoma (continued). "In one case, multiple cycles of IL13Rα2-targeted CAR T cells were administered intracranially to a glioblastoma patient, leading to a complete response for 7.5 months before recurrence." (PMID 39199630, 2024). "A patient with multifocal glioblastoma that received IL13Rα2 CAR T cells showed regression of all observed tumors for 7.5 months with no grade 3 or higher toxic effects." (PMID 39364321, 2024). "Solid tumer: HER2/IL13Ra2 (glioblastoma) and HER2/MUC] (breast cancer) CARS produce superior antitumor responses Compared to single target therapy?" (PMID 38465225, 2024). "For instance, in a case study, CAR-T cell therapy for glioblastoma patients revealed that IL13Ra2 expression was decreased following tumor recurrences." (PMID 38892913, 2024). "Another clinical trial (NCT00730613) targeting the same tumor antigen used anti-IL-13Rα2-CAR-T cells to treat three patients with recurrent glioblastoma." (PMID 39335671, 2024). "It was reported that the synthesized CAR‐T cells with dual targets of HER2 and IL‐13Rα2 showed more potent anti‐tumor activity in glioblastoma (GBM) compared with CAR‐T cells with single target." (PMID 38456710, 2024). "Recently, IL-13Rα2, as a cytokine receptor, has been employed as an anticancer immunotherapy, especially in glioblastoma and melanoma." (PMID 39598436, 2024). "(2023) assessed the effect of gastrodin (GAS) on CAR T cells targeting interleukin-13 receptor α2 antigen (IL-13Rα2 CAR T) in the brain against glioblastoma multiforme in both in vitro and in situ glioblastoma models." (PMID 39835140, 2024). "Targeted therapies employing CAR-T cells, particularly those targeting B7-H3, EGFRvIII, and IL13Rα2, demonstrate promising results in preclinical and clinical settings, highlighting their potential as novel treatment modalities for recurrent glioblastoma." (PMID 39000281, 2024). "Several tandem CARs, such as MUC1 and HER2 in breast cancer and IL13Ra2 in glioblastoma, have been evaluated in preclinical models in solid tumors." (PMID 38892913, 2024). "Extensive research has identified IL-13Rα2 overexpression not only in glioblastoma multiforme (GBM) but also in advanced stages of BCA, where it correlates with poor prognosis and enhanced metastatic capability." (PMID 38612592, 2024). "In a study by Brown and colleagues (National Clinical Trial (NCT)02208362), multi-dose treatment with IL-13Rα2-CAR-T cells resulted in complete tumor regression for nearly eight months in a patient with disseminated glioblastoma." (PMID 39335671, 2024). "For example, a phase 1 trial evaluating a locoregional delivery of IL-13Rα2-targeting chimeric antigen receptor (CAR)-T cells in recurrent high-grade glioblastomas showed promising clinical activity." (PMID 38892305, 2024). "For instance, the presence of target antigens like EGFRvIII or IL13Rα2 on glioblastoma cells has been correlated with better responses to corresponding CAR-T cell therapies." (PMID 39000281, 2024). "NCT00730613 was the first-in-human pilot study to evaluate the safety and feasibility of IL13Rα2-targeted CAR-T in recurrent glioblastoma." (PMID 39555054, 2024). "Other studies have used CARs targeting HER2 and IL-13RA2 in glioblastoma and produced some initial promising results." (PMID 39364321, 2024). "Another phase I clinical trial delivering bivalent (targeting EGFR and IL13Rα2) CAR T cells to six patients intrathecally showed efficacy with preliminary safety against recurrent glioblastoma." (PMID 39452154, 2024). "For instance, preclinical studies show that CAR-T cells targeting HER2 and IL13Rα2 antigens can effectively treat glioblastoma by overcoming tumor antigen heterogeneity and immune suppression within the TME." (PMID 39871848, 2024). "This is supported by a previous report, which suggested that IL-13Rα2 mRNA expression in glioblastoma cells is reduced under hypoxic conditions." (PMID 36830725, 2023).
glioblastoma (continued). "A novel TanCAR T cell designed to target both IL13 Ra2 and EphA2 can effectively recognize and eliminate glioblastoma tumor cells when encountering IL13Ra2 or EphA2 alone, as well as both targets simultaneously." (PMID 38067356, 2023). "Among them, two demonstrated a transient anti-glioblastoma response, marked by a notable reduction in IL13Rα2 expression in tumor cells, increased tumor necrosis volume observed on MRI scans, and the presence of T cells in tumor microfoci." (PMID 38067356, 2023). "Recently, a novel TanCAR targeting interleukin-13 receptor subunit alpha-2 (IL-13Rα2) and ephrin type-A receptor 2 (EphA2) was shown to be effective in both in vitro and in vivo glioblastoma (GBM) models." (PMID 36853475, 2023). "IL13Rα2 exhibits high expression specifically in glioblastoma cells, with absence in normal brain tissue and other healthy tissues." (PMID 38067356, 2023). "Trispecific CAR T cells that target HER2, IL13Ra2, and EphA2 offer more thorough coverage of tumor antigens and have been demonstrated to considerably extend the longevity of mice, bearing glioblastoma patient-derived xenografts." (PMID 36721153, 2023). "IL13Rα2, a high-affinity IL-13 receptor that is typically overexpressed on glioblastoma cells and barely expressed on healthy brain tissue, was one of the first targets for CAR T cell therapy of brain tumors." (PMID 36721153, 2023). "CAR[D]-T, CAR[E]-T and to some extent CAR[C]-T also showed potent cytotoxicity against glioblastoma cell lines expressing lower levels of IL13Rα2 and secreted IFN-γ in a dose-dependent manner and IL-2." (PMID 37563127, 2023). "CD19/CD22, CD19/BCMA, and HER2/IL13Ra2 have been used for the treatment of diffuse B-cell lymphoma, multiple myeloma, and glioblastoma, respectively." (PMID 36765809, 2023). "A study by Brown and colleagues was the first to assess the feasibility of this approach, using IL-13 receptor α2 (IL13Rα2)-directed CD8+ T cells to treat locally recurrent glioblastoma." (PMID 38132354, 2023). "IL-13Rα2 is highly expressed in glioblastoma (GBM) tumor cells but is rarely expressed in normal brain cells, making it an interesting target for CAR-T cell therapy in glioblastoma cancer.." (PMID 36717905, 2023). "In glioblastoma, EGFR variant III, ERBB2/HER2, and IL-13 receptor α2 (IL13Rα2) are important CAR-T cell therapy targets that have been investigated in many clinical trial studies." (PMID 37420216, 2023). "In Brown and colleagues’ study (NCT02208362), multi-dose treatment with IL-13Rα2-CAR-T cells induced a complete tumor regression for nearly 8 months in a patient with disseminated glioblastoma." (PMID 36717905, 2023). "IL13RA2 is overexpressed in various tumors, such as glioblastoma, pancreatic tumor, ovarian tumor and head and neck tumor." (PMID 37430202, 2023). "An ongoing clinical trial (NCT02208362) focusing on CAR T-cell therapy targeting IL13Rα2 for glioblastoma has demonstrated regression of all intracranial and distant spinal tumors after treatment, with this response lasting for 7.5 months." (PMID 38067356, 2023). "IL-13Rα2 promotes glioblastoma multiforme (GBM) invasiveness and proliferation, as well as acting as a negative prognostic marker in lung cancer and luminal invasive subtype breast cancer." (PMID 36830725, 2023). "In this study, we engineered a BiKE equipped with a single-domain antibody against CD16, a stimulatory molecule on NK cells, and a single-chain antibody against IL13Rα2, an antigen overexpressed in 60% of glioblastoma tumors." (PMID 37443750, 2023). "Intracranial administration of CAR-T cells targeting IL13Rα2, a monomeric high-affinity receptor for IL-13 found to be overexpressed in glioblastomas, improves T-cell persistence and antitumor efficacy against glioblastoma." (PMID 37420216, 2023). "When evaluated in vitro, all five CAR-Ts efficiently killed the human glioblastoma cell line U-87MG, which express high levels of IL13Rα2." (PMID 37563127, 2023).